VAV2 (vav guanine nucleotide exchange factor 2)
Diseases named in the same sentence as VAV2 in open-access papers (continued):
Sharing a sentence is not in itself a finding about the gene and the disease.
prostate carcinoma (5 papers, 2014 to 2025). A carcinoma that arises from epithelial cells of the prostate gland. "In agreement with these previous studies, copine-III was shown to be essential for EMP1-induced prostate cancer cell migration via the activation of the Src–Vav2–Rac1 axis by the loss-of-function and subsequent rescue experiments in our study." (PMID 29867202, 2018). "We show that EphA receptors signal via the exchange factor Vav2 to activate RhoA and that both Vav2 and RhoA are required for prostate cancer cell–cell repulsion." (PMID 24795148, 2014). "Here we show that endogenous Vav2 interacts with EphA receptors in prostate cancer cells." (PMID 24795148, 2014). "We next tested whether Vav2 is required for prostate cancer cell–cell repulsion." (PMID 24795148, 2014). "To determine the relationship between Vav2 and EMP1 in prostate cancer cells, we first confirmed that Vav2 expression levels were similar between LNCaP #2 and #17 cells." (PMID 29867202, 2018). "Here we find that Vav2 is required for RhoA activation downstream of EphA receptors and EphA receptor–RhoA-mediated CIL in prostate cancer cells." (PMID 24795148, 2014). "Since VAV2 and VAV3 are structurally related, possible functional redundancy may occur in prostate cancer, although co-expression of these VAV isoforms in human prostate tumors has not been thoroughly investigated." (PMID 40894927, 2025). "Silencing other PI3K-dependent Rac-GEFs expressed in prostate cancer cells, namely Tiam1, Vav2 or Vav3, also failed to reduce Rac1-GTP levels in PC3 cells." (PMID 32092966, 2020).
diabetic retinopathy (4 papers, 2019 to 2022). "The same G-protein can also be modulated by multiple GEFs, and Vav2 is considered as another important GEF for Rac1 activation; our recent work has implicated Vav2 in the activation of Rac1-Nox2 signaling in diabetic retinopathy." (PMID 31277234, 2019). "Experimental models have shown that the inhibitors of its GEFs- Tiam1 and Vav2, inhibit the development of diabetic retinopathy via regulating Rac1-Nox2 signaling." (PMID 34063353, 2021). "Administration of inhibitors of Tiam1 and Vav2, inhibit Rac1-Nox2 signaling in diabetic animal models, and prevent the development of diabetic retinopathy." (PMID 31277234, 2019). "Cross-talk between ceramides and Rac1 signaling via regulatory factors, including Tiam1 and Vav2, in the development of diabetic retinopathy, however, cannot be ruled out." (PMID 36202842, 2022).
metabolic syndrome (4 papers, 2020 to 2025). A cluster of metabolic risk factors for CARDIOVASCULAR DISEASES and TYPE 2 DIABETES MELLITUS. "VAV2 deficiency in mice led to reduced muscle mass, insulin responsiveness, and ultimately symptoms resembling metabolic syndrome." (PMID 40813973, 2025). "Skeletal muscle defects do arise in Vav2L332A/L332A mice though, thereby suggesting that the use of Vav2 inhibitors could eventually lead to the loss of muscle mass and the development of a metabolic syndrome condition if administered during very long periods of time." (PMID 34571735, 2021). "Consistent with this, mice bearing a Vav2 protein with decreased catalytic activity exhibit reduced muscle mass, lack of proper insulin responsiveness and, at much later times, a metabolic syndrome-like condition." (PMID 33199701, 2020). "In vivo studies demonstrated the involvement of the Rho GEFs P-Rex2, Vav2, Vav3 and PDZ-RhoGEF in glucose tolerance and/or insulin sensitivity, with deletion of these GEFs either contributing to the development of metabolic syndrome or protecting from it." (PMID 33923452, 2021). "In vivo studies in mice have shown the Rho GEFs P-Rex2, Vav2, Vav3 and PDZ-RhoGEF to be involved in glucose tolerance and/or insulin sensitivity, with deletion of these GEFs either contributing to the development of metabolic syndrome or protecting mice from this disease." (PMID 33923452, 2021).
non-small cell lung carcinoma (4 papers, 2015 to 2024). A group of at least three distinct histological types of lung cancer, including non-small cell squamous cell carcinoma, adenocarcinoma, and large cell carcinoma. "It was found that miR-331-3p could inhibit tumour cell invasion and metastasis by regulating ErbB2 and VAV2 to attenuate the epithelial–mesenchymal transition in non-small cell lung cancer." (PMID 38062510, 2023). "Additionally, VAV2 rs12002767 may influence the overall survival of patients with non-small cell lung cancer by regulating VAV2 expression." (PMID 39200159, 2024). "It has been reported that MicroRNA-195 suppressed angiogenesis and metastasis of hepatocellular carcinoma by inhibiting the expression of VEGF, VAV2, and CDC4226 and inhibited non-small cell lung cancer cell proliferation, migration and invasion by targeting MYB27." (PMID 26656154, 2015).
Skin Tumor (4 papers, 2013 to 2021). "Using genetically engineered mice, we show here that Vav2 and Vav3 favor cooperatively the initiation and promotion phases of skin tumors." (PMID 23935450, 2013). "Using this strategy, we have unveiled a Vav2/Vav3-dependent and cancer-specific autocrine/paracrine program that contributes to the initiation and promotion phases of skin tumors." (PMID 23935450, 2013). "Indeed, the generation of genetically engineered mice exhibiting varying amounts of VAV2 catalytic activity has demonstrated that the inhibition of the GEF activity prevents the generation of skin tumors in vivo." (PMID 34571765, 2021). "Adding further evidence to the connection between Vav2 and VAV3 in cancer, genetic analysis has shown that VAV2 and VAV3 depletion decreases carcinogen-induced skin tumor formation while maintaining skin homeostasis in mice." (PMID 34571765, 2021).
cervical carcinoma (3 papers, 2013 to 2019). A carcinoma arising from either the exocervical squamous epithelium or the endocervical glandular epithelium. "Then glutathione beads coupled to the chimeric proteins were incubated with a protein lysate extracted from HeLa cells –a human cervical cancer cell line in which Vav2 is robustly expressed." (PMID 23724134, 2013). "In cultured cervical cancer cells, KCC3 co-localized with the active form of Vav2 in swelling-induced actin-rich protruding sites and within lamellipodia of spreading and migrating cells." (PMID 23724134, 2013).
glaucoma (3 papers, 2010 to 2020). Increased pressure in the eyeball due to obstruction of the outflow of aqueous humor. "Here we demonstrate that deficiency of Vav2 and Vav3, guanine nucleotides exchange factors for Rho guanosine triphosphatases, leads to an ocular phenotype similar to human glaucoma." (PMID 20140222, 2010). "The Vav2/Vav3-deficient mouse has several characteristics which make it particularly useful as an animal glaucoma model." (PMID 20140222, 2010). "In addition, a genome-wide association study screening glaucoma susceptibility loci using single nucleotide polymorphisms analysis identified VAV2 and VAV3 as candidates for associated genes in Japanese open-angle glaucoma patients." (PMID 20140222, 2010). "While so far there are several reports of glaucoma associated candidate genes based on the single nucleotide polymorphisms (SNPs) study in the Japanese population, our data first suggest that VAV2 and VAV3 are susceptibility loci in Japanese primary open–angle glaucoma (POAG) cases." (PMID 20140222, 2010). "Vav2/Vav3-deficient mice should serve not only as a useful murine model of spontaneous glaucoma, but may also provide a valuable tool in understanding of the pathogenesis of glaucoma in humans, particularly the determinants of altered aqueous outflow and subsequent elevated intraocular pressure." (PMID 20140222, 2010). "We believe that Vav2/Vav3-deficient mice will serve not only as a useful murine model of spontaneous glaucoma, but may also provide a valuable tool in understanding of the pathogenesis of glaucoma in humans, particularly the determinants of altered aqueous outflow and elevated IOP." (PMID 20140222, 2010). "Vav2/Vav3-deficient mice, and to a lesser degree Vav2-deficient mice, show early onset of iridocorneal angle changes and elevated intraocular pressure, with subsequent selective loss of retinal ganglion cells and optic nerve head cupping, which are the hallmarks of glaucoma." (PMID 20140222, 2010). "In summary, we had demonstrated that Vav2/Vav3-deicient mice develop a spontaneous glaucoma phenotype." (PMID 20140222, 2010). "The most significant advantage of this mouse glaucoma model is that the deleted genes, Vav2 and Vav3, are well-focused targets that have been studied over 20 years providing a useful starting point for further investigation of the potential molecular mechanisms underlying this phenotype." (PMID 20140222, 2010). "The elevation of IOP in Vav2/Vav3-deficient mice is accompanied by an optic neuropathy characterized by selective loss of retinal ganglion cells (RGCs) and optic nerve head (ONH) excavation and is therefore consistent with glaucoma." (PMID 20140222, 2010). "The finding that Vav2-deficiency alone results in a glaucoma phenotype suggests that the absence of Vav2 plays a critical role in the development of this phenotype." (PMID 20140222, 2010). "In addition, previous studies of Vav2/3 knockout mice have shown that Vav loss-of-function results in a glaucoma phenotype, but not retinal degenerative disease." (PMID 23390493, 2013).
Glucose intolerance (3 papers, 2020 to 2025). Glucose intolerance (GI) can be defined as dysglycemia that comprises both prediabetes and diabetes. "Thus, we have found that mice carrying a Vav2 mutant protein with reduced catalytic activity exhibit impaired IGF1- and insulin-mediated PI3Kα signaling, reduced muscle mass, and increased glucose intolerance." (PMID 33199701, 2020).
head and neck cancer (3 papers, 2020 to 2025). A primary or metastatic malignant neoplasm affecting the head and neck. "Hence, given the importance of VAV2 in head-and-neck cancer, we used human oral squamous cell carcinoma cell line HSC3 to fluorescently label endogenous VAV2 and its major substrate, Rac1, by CRISPR/Cas9 gene-editing." (PMID 39744818, 2025).
oral cancer (3 papers, 2019 to 2024). "Unlike the previously identified mutations, which are located in the N-terminus of VAV2, the VAV2 mutation associated with the oral cancer family resides in the C-terminus of the protein." (PMID 31798960, 2019). "Taken together, these results strongly suggest that the mutations associated with the oral cancer family stimulate the oncogenic activity of VAV2 and IQGAP1." (PMID 31798960, 2019). "It is possible that only VAV2 or IQGAP1 mutation is responsible for the development of oral cancer in the family." (PMID 31798960, 2019). "Here, we analyzed whole-genome sequences of a family with autosomal dominant expression of oral tongue cancer and identified proto-oncogenes VAV2 and IQGAP1 as the primary factors responsible for oral cancer in the family." (PMID 31798960, 2019). "In this study, we identified VAV2 and IQGAP1 as the genetic basis of a case of oral cancer in a family." (PMID 31798960, 2019). "We also noted that some of the previously identified OSCC genes are also mutated in certain members of the oral cancer family, but they are not as dominantly penetrated as IQGAP1 and VAV2 in the family." (PMID 31798960, 2019). "Similarly, VAV2 (91%), IQGAP1 (91%), and KIAA0556 (100%) were the most frequently mutated genes in the oral cancer cell lines JHU12, PC130, SCC15, and SCC2095, as well as in seven sporadic oral cancer cases without paired normal tissue controls." (PMID 31798960, 2019).
oral squamous cell carcinoma (3 papers, 2014 to 2025). "VAV2 is an activator of RHO GTPases that promotes and maintains regenerative proliferation-like states in normal keratinocytes and oral squamous cell carcinoma (OSCC) cells." (PMID 38374399, 2024).
-dependent (2 papers, 2021). "Genes located in substance dependence, signal transduction and nervous functions pathways were down‐regulated: Cacna2d3, Epha6, Nedd4l and Vav2." (PMID 34196487, 2021). "Genes located in substance dependence, Signal transduction and also nervous functions pathways were down‐regulated: Cacna2d3, Epha6, Nedd4l and Vav2." (PMID 34196487, 2021).
adrenocortical carcinoma (2 papers, 2023 to 2025). "Another study found that the expression of an SF-1 target gene encoding the guanine exchange factor VAV2 was a critical mediator of changes in adrenocortical carcinoma cell morphology that promoted invasion in both culture and in vivo models." (PMID 36650372, 2023). "In adrenocortical carcinoma, FSCN1 is required for SF-1/VAV2-driven cell invasion." (PMID 41226387, 2025).
Arthritis (2 papers, 2015 to 2021). Inflammation of a joint. "We have also observed that Vav2 is specifically involved in the maintenance of the neutrophil long-term count in the case of Zymosan A-driven arthritis." (PMID 34205377, 2021).
breast tumors (2 papers, 2014). "We then applied our imaging-based method for direct in-tissue protein quantification, which allowed us to firstly validate our previous findings regarding IGF-IR and Rap1, and secondarily characterize the Vav2 protein expression profiles in patients with breast tumors." (PMID 25785189, 2014).
colon carcinoma (2 papers, 2014 to 2015). "Besides Vav1, Vav2, a more ubiquitously expressed member of the family of adaptors, also interacts with components of the adhesion complex, e.g. through p120-catenin in SW-480 colon cancer cells." (PMID 25426554, 2015).
diabetes (2 papers, 2019). "We have shown that the inhibition of Vav2 by its pharmacological inhibitor EHop, in addition to regulating diabetes-induced activation of Rac1-Nox2, also prevents mitochondrial damage, vascular leakage and capillary cell apoptosis." (PMID 31277234, 2019). "Pharmacological investigations involving Rac1 inhibitors have suggested Tiam1 (NSC23766), Vav2 (Ehop-016) and SoS1 as GEFs involved in sustained activation of Rac1 in the retina in diabetes." (PMID 31277234, 2019).
lymphoma (2 papers, 2009 to 2024). A malignant (clonal) proliferation of B- lymphocytes or T- lymphocytes which involves the lymph nodes, bone marrow and/or extranodal sites. "Compared to the lymphoma group, the LGBLEL group exhibited higher expression levels of CCL28, CXCL17, HCK, GNB5, NRAS, and VAV2 (p = 0.001, <0.001, <0.001, <0.001, 0.020, and <0.001, respectively) and lower expression of CCR1 (p = 0.002)." (PMID 39451532, 2024). "RT-qPCR showed that, compared to the lymphoma group, the LGBLEL group had significantly higher expression of CCL28, CXCL17, HCK, GNB5, NRAS, and VAV2 (p = 0.001, <0.001, <0.001, <0.001, =0.020, <0.001, respectively) and lower expression of CCR1 (p = 0.002)." (PMID 39451532, 2024). "WB revealed that, compared to the lymphoma group, the LGBLEL group exhibited significantly higher expression of CCL28, CXCL17, HCK, GNB5, NRAS, and VAV2 (p = 0.012, 0.005, 0.009, 0.011, 0.008, and 0.003, respectively) and lower expression of CCR1 (p = 0.014)." (PMID 39451532, 2024). "In this study, key genes from the chemokine signaling pathway—HCK, GNB5, NRAS, and VAV2—were validated, confirming their differential expression between LGBLEL and lymphoma and suggesting their important role in the malignant transformation of LGBLEL." (PMID 39451532, 2024). "Compared to the lymphoma group, the LGBLEL group showed higher expression of CCL28, CXCL17, HCK, GNB5, NRAS, and VAV2 (p = 0.012, 0.005, 0.009, 0.011, 0.008, and 0.003, respectively) and lower expression of CCR1 (p = 0.014)." (PMID 39451532, 2024). "Compared to the lymphoma group, the protein quantitative analysis of the LGBLEL group exhibited significantly differentially expressed CCL28, CCR1, CXCL17, HCK, GNB5, NRAS, and VAV2 (p = 0.003, 0.011, 0.001, 0.024, 0.005, 0.019, and 0.031, respectively)." (PMID 39451532, 2024).
Nephropathy (2 papers, 2020 to 2025). A nonspecific term referring to disease or damage of the kidneys. "In HIV‐associated nephropathy, VAV2 promotes podocyte injury through Rac1 signaling activation, with knockout experiments confirming that VAV2 inhibition significantly improves pathological alterations." (PMID 41020039, 2025).
ovarian carcinoma (2 papers, 2013 to 2014). A malignant neoplasm originating from the surface ovarian epithelium. "Thus, four genes that were validated in respect to OS (MBNL1, SPPLB2, VAV2, and CLASP1) were further tested in the independent set of 30 ovarian cancer samples." (PMID 24478986, 2014).
papilloma (2 papers, 2013 to 2020). A benign epithelial neoplasm that projects above the surrounding epithelial surface and consists of villous or arborescent outgrowths of fibrovascular stroma. "We observed that the Vav2/Vav3-dependent Tgfa, Hgf, Fgf7, and Il6 transcripts showed reduced abundance in papillomas derived from Vav2/Vav3-deficient mice when compared to the levels present in control mouse tumors." (PMID 23935450, 2013). "The cancer-linked phenotype of Vav2/Vav3-deficient mice is also quite different from that previously reported for Tiam1-deficient mice during both tumor initiation and papilloma/cSCC malignant progression." (PMID 23935450, 2013). "Expression analyses indicated that mouse papillomas and cSCCs expressed large numbers of Rho GEFs, including Vav2 and Vav3." (PMID 23935450, 2013). "This biological program may play roles in both inchoate and fully established tumors, as indicated by the similar regulation of the TPA-induced Vav2/Vav3-dependent gene signature in papillomas and cSCCs obtained from DMBA/TPA-treated mice." (PMID 23935450, 2013). "Other Vav2/Vav3-dependent (Areg, Hbegf) and -independent (Egf, Btc [ID number: 12223]) transcripts displayed similar levels in papillomas regardless of the Vav2/Vav3 expression status, further suggesting that the autocrine/paracrine defect was ameliorated in these tumors." (PMID 23935450, 2013).
rheumatoid arthritis (2 papers, 2021 to 2024). A chronic, systemic autoimmune disorder characterized by inflammation in the synovial membranes and articular surfaces. "In this study, we have demonstrated that Vav1 and Vav2 play specific roles in different types of rheumatoid arthritis models." (PMID 34205377, 2021). "Lastly, using triple Vav1–/–;Vav2–/–;Vav3–/– knockout mice, Faccio and coworkers have shown that the elimination of the three Vav family members can block the development of a neutrophil-dependent model of rheumatoid arthritis in mice." (PMID 34205377, 2021). "Genetic evidence suggests that three members of the VAV family (VAV1, VAV2 and VAV3) of signal transduction proteins could play important roles in rheumatoid arthritis." (PMID 34205377, 2021).
brain cancer (1 paper, 2022). A primary or metastatic malignant neoplasm affecting the brain. "VAV2 is overexpressed in numerous cancers, but its dysregulation has not yet been reported in brain cancers." (PMID 36551712, 2022).
buphthalmos (1 paper, 2010). "Eyes of Vav2/Vav3-deficient (Vav2−/−Vav3−/−) mice were noted to develop buphthalmos starting between 6 and 12 weeks of age." (PMID 20140222, 2010). "As histopathological examination of globes from mice with buphthalmos frequently demonstrated angle closure, we compared the iridocorneal angle histology of 20 Vav2/Vav3-deficient (Vav2−/−Vav3−/−) mice with wild-type mice at both 7 and 12 weeks of age." (PMID 20140222, 2010). "As we observed the development of buphthalmos, we assessed for elevated IOP in Vav2−/−Vav3−/−, Vav2-deficient (Vav2−/−), and Vav3-deficient (Vav3−/−) mice." (PMID 20140222, 2010). "Specifically, we show that Vav2/Vav3-deficient mice have elevated IOP, which eventually manifests as buphthalmos." (PMID 20140222, 2010).
depression (1 paper, 2022). "In addition, trans-heterozygous genetic interaction between Vav2 and Rac1J11 was observed during PTP induction, synaptic depression, and RP mobilization." (PMID 35976098, 2022).